IL6 (interleukin 6)
Diseases named in the same sentence as IL6 in open-access papers (continued):
Sharing a sentence is not in itself a finding about the gene and the disease.
bladder cancer (continued). "Moreover, a high serum level of IL-6 was associated with metastasis and poor prognosis of bladder cancers." (PMID 33923108, 2021). "Furthermore, increased IL-6 serum levels were reported to be associated with metastasis and poor prognosis of prostate, ovarian, and bladder cancers." (PMID 23637926, 2013). "EMT is a key event in invasiveness, and we examined whether this is the mechanism underlying the aggressive behavior of IL-6-positive bladder cancer." (PMID 23637926, 2013). "Therefore, in the present study, we focused on the underlying mechanisms of IL-6 and its possible usefulness for addressing the need of aggressive treatment for bladder cancer." (PMID 23637926, 2013). "The IL-6 variant genotype (C/C) was found to be associated with an increased bladder cancer risk." (PMID 22811589, 2012). "Therefore, the −174G>C polymorphism of the IL-6 may play a crucial role in bladder cancer development." (PMID 33923108, 2021). "On the other hand, these mediators and cytokines, in turn, might promote and enhance the abnormal cellular proliferation associated with polyp and bladder cancer, through generating various mediators, including inflammatory cytokines such as interleukin-6 (IL-6) and cellular growth factor (TGF-β)." (PMID 27716046, 2016). "For example, high plasma levels of IL-6 in patients with advanced kidney, breast, and bladder cancer indicate impaired effector differentiation of CD8+ cytotoxic T cells and a poor response to atezolizumab (α-PD-L1) therapy." (PMID 40238877, 2025). "Recently, the IL-6/signal transducer and activator of transcription factor 3 axis has been identified as a target in a subgroup of bladder cancer." (PMID 40353763, 2025). "Large clinical trials demonstrated that high amounts of IL-6 found in sera of advanced kidney, breast, and hepatocellular carcinoma, non-small cell lung cancer and bladder cancer patients correlate with poor response to the anti-PD-L1 antibody atezolizumab." (PMID 39281678, 2024). "Except for IL6, expressions of other genes were significantly higher in bladder cancer than in the normal sample." (PMID 39456780, 2024). "IL-6 promotes bladder cancer progression through AKT and STAT3 activations which ultimately lead to epithelial-mesenchymal transition and angiogenesis." (PMID 38172584, 2024). "The study found that BCG-induced bladder cancer cell lines led to the upregulation of NF-κB and IL-6, an effect that was abrogated by DHT." (PMID 38398136, 2024). "Compared to the parental cells (T24 and 253J), decreased MARCH7 expression was also observed in spheres, which have cancer stem-like cells (CSCs) properties (Interleukin 6 signaling maintains the stem-like properties of bladder cancer stem cells)." (PMID 38462600, 2024). "On the other hand, in vitro study showed that healthy primary bladder fibroblasts induced by bladder cancer-derived exosomes showed higher IL-6 expression than healthy primary bladder fibroblasts." (PMID 37047238, 2023). "The only earlier published results of MSC effects on 5637 and HT-1376 bladder cancer cell lines by ELISA reported cell line-dependent effects on IL-1B, IL-6, IL-8, TNFα, GM-CSF, MCP-1, TGF-β, and RANTES." (PMID 37781195, 2023). "Conversely, inflammatory CAFs, which secrete CXCL12 and IL-6 in bladder carcinoma, are essential for inducing a bladder carcinoma tumor-immunosuppressive microenvironment and promoting bladder carcinoma progression." (PMID 37853464, 2023). "Here we identify interleukin 6 (IL-6) as a correlate of poor response to atezolizumab (anti-PD-L1) in large clinical trials of advanced kidney, breast, and bladder cancers." (PMID 36599350, 2023). "Taken together, these results indicate that forced expression of HOTAIR or ProT in human bladder cancer cells enhances the expression of IL-6, TNF-α, and IL-1β." (PMID 36471329, 2022). "Of them, CXCR4 and IL6 had long been thought to be oncogenes in bladder cancer which promoted various tumor behaviors." (PMID 36263004, 2022).
bladder cancer (continued). "Our findings revealed that HME inhibits both constitutive and IL-6-induced STAT3 activation in human bladder cancer cells, supporting HME as an inhibitor of STAT3 activation." (PMID 36613579, 2022). "Long-term accumulation of toxins and glycation end products in patients with bladder cancer will increase the body's inflammatory factors, such as IL-6, CRP, TNF-α, and other acute reactive proteins." (PMID 35075365, 2022). "It was reported that the expression of plasma IL6 in patients with bladder cancer before surgery is an independent predictor of disease-specific survival." (PMID 34868901, 2021). "Myeloid cells or murine bladder cancer cells with elevated expression of S1PR1 (one of the receptors for S1P) produced more IL6." (PMID 34638448, 2021). "The bladder cancer specimens showed the IL-6 overexpression at both mRNA and protein levels compared to non-malignant tissues." (PMID 33923108, 2021). "The inhibition or knockdown of sphingomyelinase in cancer or immune cells prevented IL6 production, whereas the promotion of cellular ceramide levels by increasing sphingomyelinase expression in bladder cancer cells enhanced IL6 production." (PMID 34638448, 2021). "In vivo, CXCL-1 was shown to collaborate with IL-6 to activate endothelial cells and to promote angiogenesis in bladder cancer." (PMID 33267794, 2020). "To determine the expression of IL6 in bladder cancer samples, we performed IHC in 46 bladder cancer samples and 8 adjacent normal samples." (PMID 33244139, 2020). "To evaluate the clinical significance of IL6 in bladder cancer, we analyzed the relationship between IL6 and clinical parameters based on TCGA dataset." (PMID 33244139, 2020). "The expression of IL6 was significantly lower in bladder cancer samples (21.7%, 10/46) compared with adjacent normal tissues (75.0%, 6/8) (P = 0.009)." (PMID 33244139, 2020). "In bladder cancer, IL-6 correlated with CAF marker ACTA2 and negatively correlated with tumor purity, suggesting that CAFs were the main source of IL-6 in the TME." (PMID 32637576, 2020). "In the present study, we found that IL6 expression was downregulated in bladder cancer samples, but upregulated in advanced cancer stages and grades compared with adjacent non-malignant tissues, exactly opposite of UBC9." (PMID 33244139, 2020). "Altogether, these findings indicate that the encapsulation of BCG-CWS into the functionalized liposomes is beneficial for intracellular translocation of the cargo into bladder cancer cells, ultimately mediating the antitumor effect with IL-6 and CD4." (PMID 31817179, 2019). "We investigated IL6 expression relevance for bladder cancer progression by querying gene expression datasets of human bladder cancer specimens from TCGA and GEO genomic data platforms." (PMID 30744595, 2019). "To determine the potential of targeting IL-6 signaling in bladder cancer patients, we performed in silico analysis using IL-6 expression data acquired from public database." (PMID 30744595, 2019). "IL-6 is one of the main cytokines released from bladder cancer cells, and it recruits neutrophils to the site of the cancer, which also contributes to its anticancer effects." (PMID 31817179, 2019). "We conclude that CAFs promote aggressive phenotypes of non-invasive bladder cancer cells through an EMT induced by the secretion of IL-6." (PMID 30744595, 2019). "In particular, IL‐6 and IL‐8 were released at significant levels in primary human bladder cancer cells as well as in mouse MB49 cells." (PMID 30358081, 2019). "Because bladder cancer cells secrete IL-6 in response to BCG in vitro, the obtained results imply that BCG-CWS was successfully translocated into the 5637 cells." (PMID 31817179, 2019). "Taken together, our results reveal that IL-6 secreted from iCAFs promotes malignant behavior through the activation of the EMT program in bladder cancer cells." (PMID 30744595, 2019).
bladder cancer (continued). "Remarkably, we demonstrated that IL-6 was expressed at higher levels in bladder cancer stages III/IV than in stages I/II." (PMID 30744595, 2019). "In the current study, we found that miR-153 expression reduced IL6 secretion in bladder cancer cells, thereby inhibiting STAT3 signaling and VEGF expression." (PMID 31355138, 2019). "At the gene level, miR-153 targeted IDO1 expression and inhibited bladder cancer cell tryptophan metabolism through inhibiting IL6/STAT3/VEGF signaling." (PMID 31355138, 2019). "miR-153 targeted IDO1 expression and inhibited bladder cancer cell tryptophan metabolism through inactivating the IL6/STAT3/VEGF signaling pathway." (PMID 31355138, 2019). "Despite these preclinical data, there remains a dearth of clinical trials investigating targeted approaches, such as IL-6 signaling inhibition, particularly in bladder cancer." (PMID 30744595, 2019). "Our results are further corroborated by several recent reports showing that IL-6 concentrations are associated with increased circulating MDSC frequencies and poor prognosis in squamous cell carcinoma, bladder cancer, and head and neck cancers." (PMID 31781510, 2019). "We showed that co-culture of ASCs with human bladder cancer cells strongly induces secretion of IL-6 and IL-8, major pro-inflammatory cytokines present in the tumour microenvironment." (PMID 30310111, 2018). "Exogenous treatment of T24 bladder cancer cells using recombinant human IL6, PAI1, or CXCL1 enhanced their migratory potential." (PMID 29887999, 2018). "When ASCs were co-cultured with human primary bladder carcinoma cell lines a strong increase in protein concentration was observed for IL-6 (from 23-fold to 3.9-fold depending on the cell line) and for IL-8 (from 16.1-fold to 10.3-fold)." (PMID 30310111, 2018). "IL-6 is the most well-known traditional activator of STAT3, and positive staining of IL-6 in bladder cancer was reported to be significantly correlated with higher clinical stage and higher recurrence rate." (PMID 30091994, 2018). "We observed a substantial increase in the concentration of IL-6 and IL-8 in the secretome of adipose-derived stem cells (ASCs) co-cultured with bladder cancer cells." (PMID 30310111, 2018). "Our results showed that co-culture of ASCs and bladder cancer cells leads to a significant change in the secreted protein levels, especially IL-6 and IL-8, proinflammatory cytokines involved in tumorigenesis." (PMID 30310111, 2018). "Our study shows for the first time that DAC restores NOTCH1 expression and promotes IL-6 mediated CK5-differentiation in muscle-invasive bladder cancer cells." (PMID 29242529, 2017). "Our in vitro studies show DAC activation of immune-related (IL-6 and viral defense) and differentiation-associated (NOTCH1) transcripts and proteins in bladder cancer cell lines." (PMID 29242529, 2017). "All three bladder cancer cell lines were responsive to IL-17, as demonstrated by increased production of IL-6 and IL-8." (PMID 28931051, 2017). "IL-6 was significantly increased in the material collected from patients affected by bladder cancer, whereas TNFα showed a tendency to be induced (p = 0.08)." (PMID 26927195, 2016). "IL-6 was correlated with higher clinical stage, higher recurrence rate, and reduced survival of patients with bladder cancer." (PMID 26927195, 2016). "High level expression of DNA-methyltransferase (DNMT) 1 and IL-6 were also observed in bladder cancer cells." (PMID 27499248, 2016). "EGFR and IL6 are upstream regulators of STAT3, and all have been implicated in basal breast and bladder cancers." (PMID 27845906, 2016). "Upregulation of IL-6 was detected in the sera and urine of bladder cancer patients, as well as in tumors." (PMID 26927195, 2016). "Blockade of total IL-6 reduced the amount of fibroblast-mediated bladder cancer invasion, suggesting that IL-6 in the tumor microenvironment is necessary for TAF activation, which subsequently regulates cancer cell invasion." (PMID 27515302, 2016).
bladder cancer (continued). "Although frankincense and sandalwood essential oils activated common pathways such as inflammatory interleukins (IL-6 signaling), each essential oil had a unique molecular action on the bladder cancer cells." (PMID 25006348, 2014). "Although the role of chronic inflammation in the etiology of TCC of the bladder has not been well established, there is mounting evidence that proinflammatory cytokines play critical roles in the pathogenesis of bladder cancer, such as IL-6, IL-8 and TNF- α." (PMID 23637926, 2013). "First, we retrospectively examined the predictive value of IL-6 in bladder cancer patients only by the fraction of positive staining." (PMID 23637926, 2013). "IHC analysis for bladder TCC indicated positive staining for IL-6 in 51% of T2 –T4 bladder cancer tissues [28% (11/39) in T2 vs. 70% (32/46) in T3 –T4; P = 0.0001]." (PMID 23637926, 2013). "Taken together, our findings suggest that IL-6 is crucial for aggressive tumor growth, and the clinical outcome of bladder cancer after definite radiotherapy." (PMID 23637926, 2013). "Objectives of this study were to determine the effects of IL6 expression on cell proliferation, invasion, and tumorigenesis in bladder carcinoma cells in vitro and in vivo." (PMID 23762858, 2013). "Our experimental data indicated that the level of IL-6 is important for the aggressive tumor behavior seen in bladder cancer." (PMID 23637926, 2013). "Accordingly, the links between IL-6, angiogenesis, and promotion of bladder cancer in tumor-bearing mice were further investigated in the present study." (PMID 23637926, 2013). "We evaluated the effects of interleukin-6 expression in human bladder carcinoma cells in vitro and in vivo." (PMID 23762858, 2013). "Collectively, the results of our 3H-thymidine incorporation experiments and our xenograft animal studies indicated that IL6 attenuates the proliferation of human bladder carcinoma cells in vitro and in vivo." (PMID 23762858, 2013). "The data obtained from the present study revealed that increased IL-6 production is critical in tumor aggressiveness and prognosis of bladder cancer." (PMID 23637926, 2013). "Prior studies have indicated that BCG increased IL6 production in human and murine bladder cancer cell lines by inducing G1 cell-cycle arrest while attenuating cell proliferation, and IL6 inhibited tumor growth in murine bladder transitional carcinoma in vivo." (PMID 23762858, 2013). "Our study represents the first report showing that IL6 upregulates the expression of KAI1 in HT1376 bladder carcinoma cells, based on the results of the immunoblotting and transient gene expression analyses." (PMID 23762858, 2013). "The results of our study show that all patients with bladder cancer showed a notable increase in IL-6 peri-operatively." (PMID 23374147, 2013). "The data demonstrate that the IL-6 silencing vector significantly inhibited the growth rate of bladder cancer cells." (PMID 23637926, 2013). "Our study also represents the first report demonstrating the IL6-regulated expression of the E-cadherin, N-cadherin, and vimentin protein in bladder carcinoma cells." (PMID 23762858, 2013). "The results of our study indicate that IL6 upregulated the expression of NDRG1 in bladder carcinoma cells." (PMID 23762858, 2013). "In contrast, IL-6 treatment has been found to contribute to cell growth in human bladder cancer cells in vitro." (PMID 22962576, 2012). "The p38 MAPK pathway has also been shown to be involved in LPS-induced IL-6 secretion in pituitary adenomas and bladder cancer cells." (PMID 22583829, 2012). "The rationale of this approach is based on the fact that IL-6 and IL-10 are cytokines overexpressed in bladder carcinoma, and with a role in the interaction between cancer cells and the evironment." (PMID 23181118, 2012).
bladder cancer (continued). "In the bladder cancer sub-population, IL-6 = −0.130+1.099 protein, R Square = 0.285 (p = <0.0001); IL-8 = −0.216+0.928 protein, R Square = 0.278 (p = <0.0001); and VEGF = −0.111+0.569 protein, R Square = 0.165 (p = 0.0001)." (PMID 23300915, 2012). "For example, interleukin-6, produced by the tumour or infiltrating inflammatory cells, is recognised as a growth promoter in bladder cancer." (PMID 15726119, 2005). "A recent study in bladder cancer showed that SMARCB1-deficient tumours displayed increased IL6–janus kinase–signal transducer and activator of transcription 3 (IL6-JAK-STAT3) signalling in in vivo models and patient tumours, believed to be associated with metastasis." (PMID 40422882, 2025). "Additionally, studies have confirmed that IL-6 is upregulated in bladder cancer iCAFs, indicating that the expression of IL-6R in bladder cancer cells is suitable for responding to the IL-6 cytokine secreted by iCAFs." (PMID 38542078, 2024). "In addition, we demonstrate a correlation between Cd level and gene expression of IL-6 in cancer tissue of bladder cancer." (PMID 38072891, 2024). "Furthermore, in bladder cancer patients, risk scores were inversely linked with the expression levels of immune marker genes (CD8A, CD80, etc.)and immune activation‐related genes (IL6, IFNG, etc.)." (PMID 37771276, 2023). "Given the data above revealed sertindole as an inhibitor of STAT3 activation, either inherent in cells or induced by IL-6, we then asked whether sertindole-induced bladder cancer cytotoxicity was compromised if STAT3 remains active in sertindole-treated cells." (PMID 37511611, 2023). "For example, the levels of neutrophil peptide-1, -2, and -3 produced by neutrophils increase in bladder cancer and may promote tumor angiogenesis and growth, while the main role of macrophages is mediated by proinflammatory cytokines IL-6 and TNF-α17,20." (PMID 37670039, 2023). "Moreover, the IL-6/STAT3/PD-L1 pathway has been shown to be involved in the promotion of EMT in bladder cancer." (PMID 36230984, 2022). "Moreover, in bladder cancer it has been reported that TLR4 signaling upregulates IL-6 in a dose- and time-dependent manner." (PMID 32230799, 2020). "We examined the expression of IL-6 by iCAFs and its receptors on the bladder cancer cell line RT4." (PMID 30744595, 2019). "Urinary IL-8 has been considered a potential prognostic factor for tumor recurrence and progression following BCG therapy, while decreased IL-6 serum levels in patients with bladder cancer correlate with the appearance of myeloid-derived suppressor cells and poor prognosis." (PMID 31297119, 2019). "Furthermore, we found that IDO1 is a direct target of miR-153, which mediated miR-153 anti-tumor activity in bladder cancer via inactivating the IL6/STAT3/VEGF pathway." (PMID 31355138, 2019). "Finally, we observed that IL6 expression is up-regulated in aggressive bladder cancer and correlate with CAF marker ACTA2." (PMID 30744595, 2019). "Indeed, our current data showed that high IDO1 expression promoted IL-6 secretion in bladder cancer cells." (PMID 31355138, 2019). "Overall, our findings may serve as an attractive therapeutic target for human bladder cancer driven by IL-6 signaling." (PMID 30744595, 2019). "To investigate the effect of the CM iCAF on the activation of IL-6 signaling pathway in bladder cancer cells, we compared the expression levels of phosphorylated STAT3 (pSTAT3) and phosphorylated AKT (pAKT) in RT4 cells cultured with CM iCAF to control media (CM HF and CM HF + TGFß)." (PMID 30744595, 2019). "After its attachment and internalization into bladder cancer cells, BCG—and especially the BCG cell wall components—can induce the secretion of interleukin (IL)-6 and various other cytokines from bladder cancer cells, and the cytokines induce antitumor immunity." (PMID 30608942, 2019).